DNAJC11 (DnaJ heat shock protein family (Hsp40) member C11)
Description:
[Isoform 1]: Required for mitochondrial inner membrane organization. Seems to function through its association with the MICOS complex and the mitochondrial outer membrane sorting assembly machinery (SAM) complex.
Synonyms: FLJ10737; dJ126A5.1
Tractability: Antibody: UniProt places it where antibodies can reach, with high confidence. PROTAC: ubiquitination databases record sites on it; its protein half-life has been measured.
Gene: Protein-coding gene on chromosome 1 (6,634,168 to 6,701,924, reverse strand). Ensembl gene ENSG00000007923.
Subcellular location: Mitochondrion; Mitochondrion outer membrane (Isoform 1)
Subcellular location (Human Protein Atlas): Mitochondria
Pathways (Reactome):
Organelle biogenesis and maintenance: Cristae formation
Gene Ontology:
Molecular function: protein binding
Biological process: cristae formation; inner mitochondrial membrane organization
Cellular component: MIB complex; mitochondrial outer membrane; mitochondrion
Genetic constraint (gnomAD): Loss-of-function variants: 14 observed, 77.71 expected, observed/expected ratio (o/e) 0.18, 90% interval 0.12 to 0.28. The upper end of that interval is the gene's LOEUF score, 0.28, which puts it in group 1 of 6, group 1 being the genes least tolerant of losing a copy. Missense variants: 541 observed, 725.15 expected, observed/expected ratio (o/e) 0.75, 90% interval 0.69 to 0.8. Synonymous variants: 290 observed, 278.54 expected, observed/expected ratio (o/e) 1.04, 90% interval 0.94 to 1.15.
Homologues: Orthologues: chimpanzee DNAJC11 (99% identical), macaque DNAJC11 (99% identical), dog DNAJC11 (97% identical), guinea pig DNAJC11 (97% identical), mouse Dnajc11 (97% identical), rabbit DNAJC11 (97% identical), pig DNAJC11 (96% identical), rat Dnajc11 (96% identical), tropical clawed frog dnajc11 (88% identical), zebrafish dnajc11a (83% identical), zebrafish dnajc11b (78% identical), Drosophila melanogaster CG8531 (43% identical), and 4 more. Paralogues in human: DNAJC13 (18% identical), DNAJC21 (16% identical), DNAJC10 (15% identical), DNAJC16 (13% identical), DNAJC2 (12% identical), DNAJC1 (12% identical), DNAJC17 (11% identical), DNAJC5 (11% identical), DNAJC25 (11% identical), DNAJC5B (10% identical), DNAJC14 (10% identical), DNAJC18 (10% identical), and 8 more.
Diseases named in the same sentence as DNAJC11 in open-access papers:
DNAJC11 is named in the same sentence as 7 diseases in open-access papers, as found by Europe PMC text mining. Sharing a sentence is not in itself a finding about the gene and the disease. The quoted sentences say what the papers report.
viral infections (1 paper, 2025). "This disruption may contribute to an unfolded protein response, ER stress, and ER-associated degradation, highlighting the critical role of DNAJC11 in preserving ER integrity during viral infection." (PMID 40872740, 2025). "Although DNAJC11 is highly conserved in both vertebrates and invertebrates, its functional complexity is amplified by the presence of multiple subtypes, and its involvement in regulating viral infections has been minimally explored." (PMID 40872740, 2025).
neurodegenerative disease (2 papers, 2023 to 2025). A disorder of the central nervous system characterized by gradual and progressive loss of neural tissue and neurologic function. "In addition, distinct patterns in T61I homozygous compared to T61I heterozygous and KO mice (cluster 2) highlighted Dnajc11, a cristae-structural protein not previously implicated in CHCHD2 biology, as a potential contributor to neurodegenerative disease." (PMID 41237231, 2025).
neuromuscular disease (2 papers, 2014 to 2018). "In addition, these authors found that the OCT4B1 variant is also linked to upregulation of the chaperonin DNAJC11 which is complexed with mitofilin in the mitochondrial membrane and has been associated with neuromuscular diseases and lymphoid abnormalities." (PMID 29954368, 2018). "Finally, our study paves the way for the identification of polymorphisms and functional mutations in DnaJC11 in patients with neuromuscular diseases." (PMID 25111180, 2014). "Our findings provide the first mouse mutant for a putative MICOS protein and establish a link between DNAJC11 and neuromuscular diseases." (PMID 25111180, 2014).
cancer (1 paper, 2020). A tumor composed of atypical neoplastic, often pleomorphic cells that invade other tissues. "In the HSP40 family, DNAJC25 and DNAJC8 were positively associated with stemness in 16 and 14 cancers, respectively, while DNAJC11 and DNAJC3 were negatively associated with stemness in 25 and 25 cancers, respectively." (PMID 33225964, 2020).
infection (1 paper, 2025). The state of being infected such as from the introduction of a foreign agent such as serum, vaccine, antigenic substance or organism. "Elevated DNAJC11 expression was detected in infections caused by highly pathogenic CoVs, such as MERS-CoV and SARS-CoV-2, while significantly lower expression was observed in HCoV-229E infections." (PMID 40872740, 2025). "Building on these interesting findings, the involvement of DNAJC11 in other CoV infections was investigated by transfecting human type II alveolar epithelial cells (HPAEpiCs) with either Myc-Vec or Myc-DNAJC11, followed by infection with HCoV-229E." (PMID 40872740, 2025).
DNAJC11 also shares sentences with these, for which no sentence is quoted: breast carcinoma (1 paper); glioma (1).